NAA11 (N-alpha-acetyltransferase 11, NatA catalytic subunit)
Description:
Displays alpha (N-terminal) acetyltransferase activity. Proposed alternative catalytic subunit of the N-terminal acetyltransferase A (NatA) complex.
Synonyms: hARD2; ARD1B; ARD2
Tractability: PROTAC: ubiquitination databases record sites on it.
Gene: Protein-coding gene on chromosome 4 (79,225,694 to 79,326,061, reverse strand). Ensembl gene ENSG00000156269.
Subcellular location: Cytoplasm; Nucleus
Subcellular location (Human Protein Atlas): Centrosome; Cytosol; Golgi apparatus; Basal body; Nucleoplasm; Primary cilium
Gene Ontology:
Molecular function: protein binding; protein-N-terminal amino-acid acetyltransferase activity; protein N-terminal-serine acetyltransferase activity; protein-N-terminal-glutamate acetyltransferase activity; acyltransferase activity, transferring groups other than amino-acyl groups; protein-N-terminal-alanine acetyltransferase activity
Biological process: N-terminal protein amino acid acetylation
Cellular component: cytosol; NatA complex; nucleoplasm; cytoplasm; nucleus
Genetic constraint (gnomAD): Loss-of-function variants: 15 observed, 16.52 expected, observed/expected ratio (o/e) 0.91, 90% interval 0.61 to 1.4. The upper end of that interval is the gene's LOEUF score, 1.4, which puts it in group 5 of 6, group 1 being the genes least tolerant of losing a copy. Missense variants: 298 observed, 309.5 expected, observed/expected ratio (o/e) 0.96, 90% interval 0.88 to 1.06. Synonymous variants: 122 observed, 120.95 expected, observed/expected ratio (o/e) 1.01, 90% interval 0.87 to 1.17.
Homologues: Orthologues: macaque NAA11 (97% identical), dog NAA11 (86% identical), pig NAA11 (83% identical), rabbit NAA11 (81% identical), guinea pig NAA11 (81% identical), chimpanzee NAA11 (67% identical), Caenorhabditis elegans daf-31 (53% identical), tropical clawed frog XB5761890 (16% identical). Paralogues in human: NAA10 (83% identical), NAA20 (23% identical), NAA30 (23% identical), NAA50 (17% identical).
Diseases named in the same sentence as NAA11 in open-access papers:
NAA11 is named in the same sentence as 6 diseases in open-access papers, as found by Europe PMC text mining. Sharing a sentence is not in itself a finding about the gene and the disease. The quoted sentences say what the papers report.
melanoma (1 paper, 2025). A malignant, usually aggressive tumor composed of atypical, neoplastic melanocytes. "In contrast, in melanoma models NAA11 is highly expressed and NAA10 is not individually essential, but in these models the combined disruption of NAA10/NAA11 causes a significant growth defect." (PMID 40968372, 2025).
tumor (3 papers, 2013 to 2020). "From this analysis, the following genes were identified: NAA11, HERC5, DDX60, and HERC6 which were evaluated individually for association with tumor recurrence using the 21 Chinese patient primary tumors." (PMID 26653219, 2015). "The sensitivity of cancer cells to pharmacological targeting of NAA10 could therefore be lower in tumours, such as testicular germ cell carcinoma, where NAA11 is consistently present." (PMID 32942614, 2020).
cancer (1 paper, 2020). A tumor composed of atypical neoplastic, often pleomorphic cells that invade other tissues. "The examination of CCLE and TCGA pan-cancer data confirmed previous reports that NAA11 is epigenetically repressed in most tissues." (PMID 32942614, 2020). "Moreover, the adaptive upregulation of NAA11 could be a mechanism for cancer cells to reduce the toxicity of NAA10 inhibition." (PMID 32942614, 2020). "Within the DepMap genome-wide CRISPR knockout (KO) screen consisting of 739 cell lines of diverse tissue origin, most NATs were essential to all or to a subset of cancer cells, with the exception of NAA60, NAA80, NAA38, NAA11 and NAA16." (PMID 32942614, 2020).
NAA11 also shares sentences with these, for which no sentence is quoted: liver cancer (1 paper); Parkinsonism (1); preeclampsia (1).